KLHL11 (kelch like family member 11)
Description:
Component of a cullin-RING-based BCR (BTB-CUL3-RBX1) E3 ubiquitin-protein ligase complex that mediates the ubiquitination of target proteins, leading most often to their proteasomal degradation.
Synonyms: FLJ10572
Tractability: Antibody: UniProt predicts a signal peptide or a membrane-spanning region. PROTAC: ubiquitination databases record sites on it.
Gene: Protein-coding gene on chromosome 17 (41,848,518 to 41,865,423, reverse strand). Ensembl gene ENSG00000178502.
Subcellular location (Human Protein Atlas): Nucleoplasm; Nuclear membrane
Pathways (Reactome):
Immune System: Antigen processing: Ubiquitination & Proteasome degradation
Metabolism of proteins: Neddylation
Gene Ontology:
Molecular function: protein binding; ubiquitin-like ligase-substrate adaptor activity
Biological process: proteasome-mediated ubiquitin-dependent protein catabolic process
Cellular component: Cul3-RING ubiquitin ligase complex; cytoplasm; cytosol
Genetic constraint (gnomAD): Loss-of-function variants: 26 observed, 55.72 expected, observed/expected ratio (o/e) 0.47, 90% interval 0.34 to 0.65. The upper end of that interval is the gene's LOEUF score, 0.65, which puts it in group 2 of 6, group 1 being the genes least tolerant of losing a copy. Missense variants: 608 observed, 900.62 expected, observed/expected ratio (o/e) 0.68, 90% interval 0.63 to 0.72. Synonymous variants: 330 observed, 349.1 expected, observed/expected ratio (o/e) 0.95, 90% interval 0.86 to 1.03.
Homologues: Orthologues: chimpanzee KLHL11 (100% identical), macaque KLHL11 (100% identical), dog KLHL11 (99% identical), pig KLHL11 (99% identical), rat Klhl11 (97% identical), mouse Klhl11 (97% identical), guinea pig KLHL11 (93% identical), tropical clawed frog klhl11 (71% identical), zebrafish klhl11 (70% identical), rabbit KLHL11 (58% identical), Drosophila melanogaster BTBD9 (7% identical), Drosophila melanogaster lute (6% identical), and 2 more. Paralogues in human: ABTB3 (20% identical), ABTB2 (20% identical), BTBD9 (9% identical), ABTB1 (7% identical), BTBD3 (7% identical), BTBD6 (7% identical), BTBD2 (7% identical), BTBD1 (7% identical), SPOPL (6% identical), SPOP (5% identical), KBTBD4 (5% identical).
Diseases named in the same sentence as KLHL11 in open-access papers:
KLHL11 is named in the same sentence as 29 diseases in open-access papers, as found by Europe PMC text mining. Sharing a sentence is not in itself a finding about the gene and the disease. The quoted sentences say what the papers report.
encephalitis (9 papers, 2023 to 2026). An acute inflammatory process affecting the brain parenchyma. "KLHL11 encephalitis exhibits a strong association with malignancies and is classified as a paraneoplastic syndrome (PNS)." (PMID 41280942, 2025). "Due to intracellular localization of KLHL11 protein, the pathogenic mechanism of KLHL11 encephalitis is considered to be T-cell-mediated." (PMID 41280942, 2025). "This case demonstrates an association between KLHL11 encephalitis and dual malignancies (ductal breast carcinoma and pulmonary adenocarcinoma), expanding the known tumor spectrum in female patients." (PMID 41280942, 2025). "Herein, we describe a case of anti-KLHL11 encephalitis in which the patient presented with recurrent staring spells as the chief complaint, accompanied by transient mild cerebella signs." (PMID 42039192, 2026). "This case highlights the diverse clinical manifestations and staged progression of anti-KLHL11 encephalitis, which warrants full recognition in clinical practice." (PMID 42039192, 2026). "Kelch-like protein 11 (KLHL11) encephalitis is a rare clinical condition characterized by autoimmune-mediated encephalitis associated with the presence of KLHL11 antibodies, which commonly presents with ataxia, diplopia, vertigo, hearing loss, and seizures." (PMID 41280942, 2025). "Some KLHL11 encephalitis patients coexisted with other paraneoplastic antibodies, including anti-leucine zipper 4, anti-Ma2 and anti-Hu." (PMID 41280942, 2025). "Background and Aims: Anti‐Kelch‐like protein 11 (KLHL11) encephalitis was discovered in 2019 in middle‐aged males with testicular seminoma and rhombencephalitis." (PMID 40542572, 2025). "Current studies showed that KLHL11 encephalitis contributed to pathogenesis through cytotoxic T-cell-mediated neuronal injury and loss." (PMID 41280942, 2025). "KLHL11 encephalitis primarily contributes to pathogenesis through T-cell-mediated inflammatory responses and specific T-cell reactions." (PMID 41280942, 2025). "Anti-Kelch-like protein 11 (KLHL11) antibody encephalitis is a rare clinical condition characterized by autoimmune-mediated encephalomyelitis associated with the presence of KLHL11 antibodies." (PMID 37954647, 2023). "The clinical manifestations of anti-KLHL11 antibody encephalitis vary widely, and timely identification and treatment can improve prognosis." (PMID 37954647, 2023). "Additionally, this case expands the current understanding of anti-KLHL11 antibody encephalitis regarding its clinical presentations, imaging features, and therapeutic responsiveness." (PMID 42039192, 2026). "This study aimed to comprehensively define phenotype and outcome of KLHL11‐encephalitis." (PMID 40542572, 2025). "KLHL11 encephalitis was initially identified in a male patient with seminoma." (PMID 41280942, 2025). "Anti-kelchlike protein 11 (KLHL11) encephalitis was first reported in 2019." (PMID 39575244, 2024). "Current studies show that KLHL11 encephalitis is mediated by T cell immunity." (PMID 39575244, 2024). "Notably, to date, no cases of KLHL11 encephalitis co-occurring with breast cancer have been documented in the literature, and the present case represents the first documented instance of KLHL11 encephalitis occurring concomitantly with both ductal breast carcinoma and primary lung adenocarcinoma." (PMID 41280942, 2025).
autoimmune encephalitis (4 papers, 2023 to 2026). Inflammation of the brain secondary to an immune response triggered by the body itself. "Serum and cerebrospinal fluid (CSF) were identified as positive for anti-KLHL11 antibodies, leading to a diagnosis of autoimmune encephalitis associated with KLHL11 antibodies." (PMID 37954647, 2023). "For patients suspected of autoimmune encephalitis, dynamic re-examination of cranial imaging and CSF, as well as timely KLHL11-IgG testing, are critical for early diagnosis and prompt treatment, thereby improving prognosis." (PMID 42039192, 2026). "The transfection cytology methods were used to detect autoimmune encephalitis antibodies (NMDAR, AMPAR1, AMPAR2, LGI1, CASPR2, GABABR, DPPX, IgLON5, GlyRα1, GABAARα1, GABAARβ3, mGluR1, mGluR5, D2R, Neurexin-3α, GAD65, KLHL11, gAChR, AQP4, MOG, GFAP) in CSF and serum." (PMID 40771880, 2025).
seminoma (4 papers, 2023 to 2025). A radiosensitive malignant germ cell tumor found in the testis (especially undescended), and extragonadal sites (anterior mediastinum and pineal gland). "Antibody biomarkers continue to be characterized (e.g., KLHL-11 associated with seminoma in men with brainstem encephalitis)." (PMID 36781586, 2023). "In 2019, the Human PhIP-Seq Library v2 was used to discover antibodies to kelch-like protein 11 (KLHL11) in the cerebrospinal fluid and serum of 13 patients with seminoma-associated paraneoplastic encephalitis." (PMID 39295784, 2024). "Notably, among patients with anti-KLHL11 antibody positivity, ataxia is frequently accompanied by encephalopathy, and in the majority of reported cases (11 out of 13), a seminoma was also diagnosed." (PMID 40881707, 2025).
testicular germ cell tumor (4 papers, 2023 to 2026). A germ cell tumor arising from the testis. "Compared with the remainder of the cohort, KLHL‐11‐IgG positivity associated with male sex (p ≤ 0.001), hearing loss (<0.001) and the presence of a testicular germ cell tumor (<0.001)." (PMID 39708293, 2025).
testicular seminoma (4 papers, 2021 to 2026). A malignant germ cell tumor arising from the testis. "In contrast, KLHL11 has a strong association with testicular seminoma in men." (PMID 34489848, 2021). "The newly described anti-Kelch-like protein 11 (KLHL11) antibody also exhibits a strong male predominance, linking rhombencephalitis to testicular seminomas." (PMID 41562781, 2026).
Ataxia (3 papers, 2024 to 2025). Ataxia refers to impaired coordination of voluntary muscle movement. "Recently, two antibodies, directed against kelch-like family member 11 (KLHL11) and glutamate kainate receptor subunit 2 (GluK2), also associated with cerebellar ataxia, have been described." (PMID 39735552, 2024). "MATCH score (male, ataxia, testicular cancer and hearing alterations) was designed to facilitate the identification of patients that should be tested for KLHL11 antibodies with a cut-off ≥ 4 points." (PMID 41280942, 2025). "As MOG, AQP-4, KLHL11, and GluK2 antibodies have been identified in NMDAR-E patients and have been associated with neurological symptoms including ataxia, we tested available sera for all four antibodies." (PMID 39735552, 2024). "In more than half of our patients with NMDARE-associated ataxia, we were able to exclude the presence of MOG, AQP-4, KLHL11, and GluK2 antibodies, all of which have previously been associated with both NMDAR-E and CNS neurological deficits including ataxia." (PMID 39735552, 2024). "Serum was tested negative for MOG, AQP-4, KLHL11, and GluK2 antibodies in five of eight patients with cerebellar ataxia (Cases 3–5, 7, and 8)." (PMID 39735552, 2024). "Cerebellar ataxia in NMDAR-E may not be explained by concomitant KLHL11, MOG, AQP-4, or GluK2 autoimmunity." (PMID 39735552, 2024). "Cerebellar ataxia with and without additional neurological symptoms is commonly neither explained by concomitant AQP-4 antibody-positive NMOSD or MOGAD nor KLHL11 or GluK2 antibodies." (PMID 39735552, 2024). "In all five patients with cerebellar ataxia tested, MOG, AQP-4, GluK2, and KLHL11 antibodies were negative." (PMID 39735552, 2024).
breast carcinoma (3 papers, 2023 to 2025). "A subacute, progressive ataxic syndrome in the proper clinical context should therefore raise suspicion for a PNS related to Hodgkin lymphoma (anti-DNER), breast cancer (anti-Ri/ANNA-2), testicular cancer (anti-KLHL11), or others." (PMID 37239077, 2023).
lung adenocarcinoma (3 papers, 2021 to 2026). A carcinoma that arises from the lung and is characterized by the presence of malignant glandular epithelial cells. "A previously unidentified function of KLHL7 (Kelch Like Family Member 7) and KLHL11, components of the BCR (BTB-CUL3-RBX1) E3 ubiquitin ligase complex, in lung adenocarcinoma genomic instability was also suggested (q = 0.0003, 0.04, respectively)." (PMID 34070461, 2021).
paraneoplastic cerebellar degeneration (1 paper, 2023). A rare, immune-mediated disorder characterized by cerebellar degeneration due to the presence of an often undetected malignancy (usually carcinoma or lymphoma) in an anatomic site other than the cerebellum. "SKOR2 autoantibodies may serve as a marker of a cytotoxic T-cell–mediated injury directed through T-cell receptors recognizing SKOR2 peptides, similar to PCA1 or KLHL11 autoantibody-associated paraneoplastic cerebellar degeneration." (PMID 37795104, 2023).
testicular tumors (1 paper, 2024). "Recently, anti-Kelch-like protein 11 (KLHL11) Abs have also been described in association with testicular tumors and brainstem-cerebellar involvement." (PMID 36991252, 2024).
Tinnitus (1 paper, 2024). Tinnitus is an auditory perception that can be described as the experience of sound, in the ear or in the head, in the absence of external acoustic stimulation. "Similarly, hearing loss or tinnitus antedate the development of cerebellar/brainstem dysfunction in nearly 25% of the patients with anti-KLHL11 Abs." (PMID 36991252, 2024).
Tumor (2 papers, 2025 to 2026). "KLHL11 IgG may trigger immune attacks against neurons and tumor cells by activating antigen-presenting cells (such as dendritic cells) and T-cell responses." (PMID 41280942, 2025).
KLHL11 also shares sentences with these, for which no sentence is quoted: testicular cancer (2 papers); adenocarcinoma (1); atherosclerosis (1); Autoimmunity (1); cancer (1); Cerebellar ataxia (1); ductal breast carcinoma (1); Encephalopathy (1); germ cell tumor (1); Hodgkins lymphoma (1); leukemia (1); lung carcinoma (1); meningitis (1); neurodegenerative disease (1); non-small cell lung carcinoma (1); paraneoplastic neurologic syndrome (1); Vertigo (1).